SNORD115-45 (small nucleolar RNA, C/D box 115-45)
Synonyms: HBII-52-45; SNORD115-48
Gene: Small nucleolar RNA gene on chromosome 15 (25,264,510 to 25,264,590, forward strand). Ensembl gene ENSG00000212380.
Gene Ontology:
Biological process: RNA processing
Cellular component: nucleolus
Homologues: Orthologues: chimpanzee SNORD115 (100% identical), macaque SNORD115 (96% identical), dog SNORD115 (70% identical). Paralogues in human: SNORD115-32 (74% identical), SNORD115-39 (74% identical), SNORD115-11 (73% identical), SNORD115-20 (73% identical), SNORD115-22 (73% identical), SNORD115-29 (73% identical), SNORD115-36 (73% identical), SNORD115-38 (73% identical), SNORD115-43 (73% identical), SNORD115-44 (73% identical), SNORD115-10 (72% identical), SNORD115-12 (72% identical), and 37 more.